FAR1 (fatty acyl-CoA reductase 1)
Description:
Catalyzes the reduction of saturated and unsaturated C16 or C18 fatty acyl-CoA to fatty alcohols. It plays an essential role in the production of ether lipids/plasmalogens which synthesis requires fatty alcohols. In parallel, it is also required for wax monoesters production since fatty alcohols also constitute a substrate for their synthesis (By similarity).
Synonyms: MLSTD2; FLJ22728; SDR10E1; CSPSD; PFCRD
Tractability: Antibody: UniProt predicts a signal peptide or a membrane-spanning region. PROTAC: ubiquitination databases record sites on it; its protein half-life has been measured.
Target class: Enzyme; Oxidoreductase
Gene: Protein-coding gene on chromosome 11 (13,667,462 to 13,732,367, forward strand). Ensembl gene ENSG00000197601.
Subcellular location: Peroxisome membrane
Subcellular location (Human Protein Atlas): Peroxisomes
Pathways (Reactome):
Metabolism: Wax biosynthesis
Gene Ontology:
Molecular function: alcohol-forming long-chain fatty acyl-CoA reductase activity; protein binding; oxidoreductase activity; alcohol-forming very long-chain fatty acyl-CoA reductase activity; oxidoreductase activity, acting on the aldehyde or oxo group of donors, NAD or NADP as acceptor
Biological process: ether lipid biosynthetic process; glycerophospholipid biosynthetic process; long-chain fatty-acyl-CoA metabolic process; wax biosynthetic process; fatty acid derivative metabolic process; lipid biosynthetic process
Cellular component: peroxisomal membrane; peroxisome
Genetic constraint (gnomAD): Loss-of-function variants: 15 observed, 38.83 expected, observed/expected ratio (o/e) 0.39, 90% interval 0.26 to 0.6. The upper end of that interval is the gene's LOEUF score, 0.6, which puts it in group 2 of 6, group 1 being the genes least tolerant of losing a copy. Missense variants: 256 observed, 478.35 expected, observed/expected ratio (o/e) 0.54, 90% interval 0.48 to 0.59. Synonymous variants: 158 observed, 170.64 expected, observed/expected ratio (o/e) 0.93, 90% interval 0.81 to 1.06.
Gene-disease validity (ClinGen):
ClinGen rates the evidence that FAR1 causes each of these diseases.
fatty acyl-CoA reductase 1 deficiency (autosomal recessive): Moderate.
Homologues: Orthologues: chimpanzee FAR1 (99% identical), macaque FAR1 (99% identical), rabbit FAR1 (99% identical), mouse Far1 (98% identical), guinea pig Far1 (97% identical), pig FAR1 (97% identical), dog FAR1 (93% identical), rat Far1 (89% identical), tropical clawed frog far1 (86% identical), zebrafish far1 (78% identical), Caenorhabditis elegans fard-1 (39% identical), Drosophila melanogaster CG5065 (39% identical), and 16 more. Paralogues in human: FAR2 (59% identical).